BMP2 (bone morphogenetic protein 2)
Diseases named in the same sentence as BMP2 in open-access papers (continued):
Sharing a sentence is not in itself a finding about the gene and the disease.
breast cancer (continued). "Therefore, we hypothesized that CCN6 antagonized BMP signaling via binding to BMP2, as was observed in breast cancer cells." (PMID 37590989, 2023). "TGF-β and BMP2 signaling plays significant roles throughout breast cancer (BC) development and promote metastasis by triggering bone metastasis genes IL11 and CTGF in vivo." (PMID 34326372, 2021). "BMP2, one of isoforms of BMPs, had been shown to be overexpressed in several types of cancers including hepatocarcinoma, non-small lung cancer, breast cancer, gastric, colon cancer, bladder carcinoma, oral squamous carcinoma, prostate cancer, liposarcomas and ovarian cancer." (PMID 28455969, 2017). "Thus, RUNX2 functions as a master mediator during the transformation of epithelial breast cancer cells into osteomimetic cells under the induction of CAF/BMP2, and the expression of BRGs is repressed by the TGF-β/SMAD/RUNX2 signaling pathway but induced by the BMP/SMAD/RUNX2 signaling pathway." (PMID 27806311, 2016). "Thus, RUNX2 functions as a master mediator during the transformation of epithelial breast cancer cells into ostomimetic cells under CAF/BMP2 induction, and the expression of BRGs was repressed in the TGF-β/SMAD/RUNX2 signaling pathway, but induced in the BMP/SMAD/RUNX2 signaling pathway." (PMID 27806311, 2016). "Therefore, we speculated that the ectopic co-expression of BRGs in breast cancers may be derived from epithelial cancer cells that have undergone EMT followed by BMP2 induction in the CAF-enriched tumor microenvironment." (PMID 27806311, 2016). "However, BMP-2 overexpression has been demonstrated to result in changes in cell morphology and increased cell motility and invasiveness in the pancreatic, gastric, prostate and breast cancer cells." (PMID 25271422, 2014). "In addition, ectopic expression of BMP-2 stimulated angiogenesis in developing tumors and resulted in significantly increased local invasion and metastasis in melanoma, lung cancer cells, and breast cancer cells." (PMID 25271422, 2014). "Additionally, BMP2 has been shown to induce p21 expression in breast cancer cells." (PMID 24053318, 2013). "Specifically, in this study, we perform immunohistochemical and bioinformatic analyses to investigate the possible prognostic role of vimentin, SDF-1, BMP-2, BMP-4, PTX3, OPN, RANKL, and Runx2 on a large cohort of breast cancer patients." (PMID 39859358, 2025). "The bioinformatics analysis provided valuable insights into the possible prognostic and therapeutic significance of BMP-2, BMP-4, SDF-1, and vimentin in breast cancer." (PMID 39859358, 2025). "TCGA data analysis demonstrated that mRNA expression of BMP2 and BMP6 are significantly downregulated in breast cancer patients when compared to normal breast tissue." (PMID 38731813, 2024). "For example, BMP2 and BMP6 inhibit cell proliferation whilst BMP7 promotes the proliferation of breast cancer cells." (PMID 37333824, 2023). "BMP2, BMP4, GDF11 and TGFBR2 had relatively higher levels in bone metastases of breast cancer while BMP5, BMP7, BMPR2, BMPR1A and ACVR2A presented lower expression in the bone metastases, in the E-MTAB-4003 dataset." (PMID 37333824, 2023). "Recombinant BMP2 induces EMT and stemness of breast cancer cells via the Rb and CD44 signaling pathways, which leads to metastasis." (PMID 35846378, 2022). "BMP-2 induces EMT and stemness of breast cancer cells through the Rb and CD44 signaling pathways, which act not only via Smad-dependent pathways but also via the PI3 kinase-Akt signaling pathway." (PMID 35693928, 2022). "Previous studies have shown that BMP-2 expression was significantly correlated with the presence of microcalcifications and BMP-2 can induce breast cancer cells to acquire osteoblastic characteristics." (PMID 34983451, 2022). "Several BMPs, including BMP2, BMP6, BMP9, BMP10, BMP15, and GDF9a inhibit the proliferation of breast cancer cells, whereas BMP4 and BMP7 can either promote or inhibit proliferation in different contexts." (PMID 35846378, 2022).
breast cancer (continued). "Starting from these considerations, this study aims to investigate the possible different roles of cytoplasmic (here identify as BMP-2) and nuclear (here identify as nBMP-2) BMP-2 in both the EMT and microcalcifications production in human breast cancer." (PMID 32498363, 2020). "Starting from these considerations, this study aimed to investigate the possible different role of cytoplasmic BMP-2 and nBMP-2 in both EMT and microcalcifications production in human breast cancer." (PMID 32498363, 2020). "We therefore looked for co-expression of GREM1 and its preferred BMPs, BMP2, BMP4 or BMP7, in human breast cancer cell lines using Expression Atlas." (PMID 31694641, 2019). "BMP-2 also promoted the formation of tumor spheroids and increased the population of CD44+/CD24− cells in MCF-7 breast cancer cells." (PMID 29339728, 2018). "BMP2, reported to promote invasion and progression of MCF-7 breast cancer cells, was substantially elevated in all three metastatic lines, whereas the breast cancer metastasis suppressor gene BMP4 was suppressed in each of the three variants." (PMID 29720474, 2018). "Overall, this is the first study demonstrating that BMP-2 is a driving factor for promoting EMT and breast cancer stemness via Rb and CD44 signaling pathways." (PMID 29339728, 2018). "Bone morphogenetic protein 2 (BMP-2) has been reported to facilitate epithelial-to-mesenchymal transition (EMT) and bone metastasis in breast cancer xenograft models." (PMID 28725489, 2017). "In summary, this is the first study demonstrating that BMP-2 promotes EMT and breast cancer stemness via Rb and CD44 signaling pathways." (PMID 28725489, 2017). "Tan and coworkers showed that breast cancer cells with induced EMT exhibited an elevated level of bone-related genes (BRGs) and osteoblast-like features in an exposure to BMP-2." (PMID 28733469, 2017). "In breast cancer cells, SOSTDC1 modestly increases Wnt3a signalling, decreases BMP-7 signalling, whilst eliciting little effect on BMP-2-induced signalling." (PMID 28733469, 2017). "By analyzing the immunohistochemical images and immunoreactive scores of BMP-2, CD44, and Rb proteins in each sample, we confirmed that BMP-2 expression was positively correlated with CD44 expression in the breast carcinoma cohort." (PMID 28725489, 2017). "In human dermal microvascular endothelial cells, BMP-2 induces Id1 expression and cooperates with VEGF signaling to promote angiogenesis in murine breast cancer xenograft models." (PMID 27661009, 2016). "By forming a heterodimer with BMP7, BMP2 acts as a TGF β antagonist and prevents bone metastases in a mouse model of breast cancer." (PMID 24944582, 2014). "More precisely, the effects of BMP2 and BMP7 treatments on transcription in MCF-7 and MDA-MB-468 breast cancer cell lines, respectively, have been analyzed using cDNA microarrays of limited content (from several hundreds to 14, 500 gene probes)." (PMID 22118688, 2011). "For down-regulated genes, bone morphogenetic protein 2 (BMP2A), a multi-functional growth factor belonging to the transforming growth factor-β superfamily was decreased in CCA fibroblasts as reported in breast cancer-derived fibroblasts." (PMID 20096135, 2010). "Several studies on the overexpression of BMPs, such as BMP-2, BMP-4, and BMP-7 in mammary tumor cells are suggestive of a role of BMPs in breast cancer development." (PMID 17997862, 2007). "Notably, pathways such as BMP2 targets, ERBB2 in breast cancer, and arachidonic acid metabolism were enriched, indicating their upregulation." (PMID 40356901, 2025). "The findings here reported suggest that vimentin, BMP-2, BMP-4, and SDF-1 could be independent prognostic biomarkers in breast cancer, providing insights beyond traditional clinical factors." (PMID 39859358, 2025).
breast cancer (continued). "After in vitro induction with rosiglitazone and bone morphogenetic protein-2 (BMP-2), post-EMT breast cancer cells were transformed into adipocytes expressing various adipocyte markers and responding to isoproterenol and insulin in the same manner as adipocytes." (PMID 37935080, 2024). "In four main subtypes of breast cancer, elevated expression of BMPR1B and ACVR2B were seen in Luminal A subtype, while BMP4, GDF15 and ACVR1B were higher in Luminal B, TGFBR1 and BMP8A were higher in HER2 positive, BMP2, BMP6 and GDF5 were higher in TNBC." (PMID 37333824, 2023). "BMP2, BMP4, GDF15 and TGFBR1 were significantly correlated with T stage of breast cancer." (PMID 37333824, 2023). "Therefore, it is possible that increased miR-200c/141 levels reduce MXRA8 expression which in turn decreases the expression of breast cancer progression genes like ADAMTS1 and BMP2 potentially through increasing histone methylation." (PMID 37762032, 2023). "Several studies have demonstrated that BMP-2 could also upregulate some bone metabolic factor, e.g., RANKL and RUNX2, to induce breast cancer cells acquire osteoblastic characteristics." (PMID 34983451, 2022). "Sostdc1 blocks the Smad phosphorylation induced by BMP7 without diminishing BMP2 or Wnt3a-induced signalling in breast cancer cells, indicating that Sostdc1 is a clinically important extracellular regulator of various signalling pathways in breast cancer." (PMID 36338475, 2022). "Indeed, concomitantly to intrinsic SC alterations, an increase in soluble BMP2 and BMP4, compared to healthy individuals, was detected within the tumor microenvironment of leukemia and breast cancer." (PMID 35047500, 2021). "Moreover, BMP2 promotes bone metastasis of breast and prostate cancer via the AKT pathway, but BMP9 was shown to inhibit the AKT signaling in breast cancer and, thus, suppresses the formation of bone metastases." (PMID 34064589, 2021). "Similarly, in MDA-MB-231 and Hs578T breast cancer cells, which expressed endogenous TrkB, the BRE transcriptional activity increased in response to K252a and BMP-2 treatments." (PMID 32731498, 2020). "Similarly, bone morphogenetic protein 2 (BMP-2) degrades Rb through ubiquitinylation in breast cancer cell lines as well as clinical samples; thus resulting in the development of breast cancer stem cells (BCSs) and enhancement of EMT signaling." (PMID 32566256, 2020). "Our in vitro and in vivo findings highlight the crucial roles of BMP-2, Rb, and CD44 in breast cancer metastasis, which may provide new strategies for determining the prognosis and treatment of advanced breast cancer." (PMID 29339728, 2018). "To investigate a potential involvement of the BMP family in telomerase activity, we examined the effects of BMP2, BMP4, BMP5, BMP6 and BMP7 on telomerase activity by spiking the medium of cultured human breast cancer MCF-7 cells with purified recombinant human cytokines." (PMID 27696331, 2017). "Our results indicated that BMP-2 promoted EMT and migration/invasion of breast cancer cells." (PMID 28725489, 2017). "We have provided an insight into the effects of BPA and B(a)P on the response of SCs to BMP2 and BMP4, which could contribute to very early stages of breast cancer initiation." (PMID 27740625, 2017). "Our in vitro and in vivo findings highlight the crucial roles of BMP-2, Rb, and CD44 in breast cancer metastasis, which may provide new strategies for the treatment and prognosis of advanced breast cancer." (PMID 28725489, 2017). "Bone morphogenetic protein 2 (BMP2) and BMP4 are key regulators of the fate and differentiation of human mammary epithelial stem cells (SCs), as well as of their niches, and are involved in breast cancer development." (PMID 27740625, 2017).
breast cancer (continued). "BMP-2 under routine culture conditions, shows pro-apoptotic effect in MCF-7 breast cancer cells, in which the expression and function of apoptosis related genes, particularly protein kinase R (PKR), and subsequent activation of its substrate eIF2α are regulated by BMP signalling." (PMID 28733469, 2017). "BMP-2/-7 heterodimer, the most efficient stimulator of BMP signaling, diminishes the ALDHhi/CD44hi/CD24low CSC pool and effectively reduces the activation of TGF-β-driven SMAD signaling pathway, thereby inhibiting tumor invasion in breast cancer." (PMID 27661009, 2016). "Compared to infiltrating breast carcinomas without microcalcifications, infiltrating breast carcinoma with microcalcifications upregulate BMP-2 and OPN, allowing them to acquire a mesenchymal characteristics and osteoblast-like phenotype." (PMID 27023622, 2016). "We also used a reporter construct consisting of the phospho-SMAD1/5/8 responsive ID1 promoter upstream of a luciferase gene to compare the effects of BMP2 and AB215 treatment on the human breast cancer cell lines MCF7, T47D and SK-BR-3 in the absence or presence of E2 treatment." (PMID 25070479, 2014). "BMP2’s and AB215’s inhibition of breast cancer cells growth was investigated." (PMID 25070479, 2014). "We further examined the signaling properties of AB215 in human MCF7 breast cancer cells and found that, similar to what was observed in C2C12 cells, AB215 produces prolonged and enhanced SMAD1/5/8 phosphorylation when compared to that induced by BMP2." (PMID 25070479, 2014). "Immunohistochemical analysis was performed to evaluate the expression of vimentin, BMP-2, BMP-4, RANKL, Runx2, OPN, PTX3, and SDF-1, while Kaplan—Meier plots were used to assess their prognostic impact on overall survival in a dataset of 2976 breast cancer patients." (PMID 39859358, 2025). "Therefore, the EMT phenomenon in breast cancer seems to be related to the expression of BMP-2 rather than nBMP-2." (PMID 32498363, 2020). "In breast cancer Hs578T cells, BMP4 slightly downregulated asporin and phosphorylation of focal adhesion kinase (FAK) at tyrosine 397 (2.4 and 2.1 mean fold downregulation, respectively), while BMP2 did not cause any consistent changes (1.2 mean fold downregulation)." (PMID 27409832, 2016). "Furthermore, higher levels of BMP2, BMP6 and GDF5 were revealed in triple negative breast cancer (TNBC) whilst BMP4, GDF15, ACVR1B, ACVR2B and BMPR1B were relatively higher in Luminal type BC." (PMID 37333824, 2023). "On the other hand, Reverse Phase Protein Array (RPPA) data for the breast cancer patient cohort, where it is possible to analyze the change in β-CATENIN protein level, did not include either BMP2/BMP6 or phosphorylated SMADs (SMAD1/SMAD5) or direct target genes of BMP pathway such as ID1–3." (PMID 38731813, 2024). "This implies that the downregulation of BMP2 and BMP6 might affect the survival and progression of breast cancer regardless of molecular subtype." (PMID 38731813, 2024).
diabetes (41 papers, 2015 to 2025). "Recombinant human BMP2 significantly stimulated bone formation in diabetic animal and enhanced bone regeneration in normal animals which means that BMP2 may be beneficial in treating the deficient intramembranous bone formation in diabetes." (PMID 34258293, 2021). "Hence, the use of therapeutic agents which could target BMP-2 and sclerostin might prove beneficial in improving diabetes-linked osteoporosis." (PMID 35928902, 2022). "Previous work has shown that BMP2 inhibits NLRP3 inflammasome activation during the development of type 2 diabetes mellitus-induced cardiomyocyte injury." (PMID 39334820, 2024). "Accordingly, interaction effect analysis showed that diabetes in women increases BMP-2 and osteocalcin levels." (PMID 37848892, 2023). "BMP-2 expression exhibited a similar trend in a rat model of myocardial damage and diabetes, and researchers also found that exogenous BMP-2 alleviated doxorubicin- and high glucose-induced inflammation and pyroptosis in vitro." (PMID 36909186, 2023). "Bmp2 levels increased significantly in diabetes group (28.6 ± 2.6%) with reference to control group (4.16 ± 1.5%)." (PMID 36805334, 2023). "The pro-inflammatory factor BMP-2 is upregulated in islets of Langerhans from individuals with diabetes and acts as an inhibitor of beta cell function and proliferation." (PMID 37407581, 2023). "The expression of tbx20 and bmp2 was also increased significantly during diabetes as compared with control." (PMID 36805334, 2023). "Nevertheless, further investigations are warranted to elucidate the role of BMP2 regulating glucose and lipid homeostasis and its impact in the pathogenesis of metabolic diseases such as obesity, diabetes and NAFLD." (PMID 35614516, 2022). "In our study too, we observed that HFD-induced diabetes resulted in reduced bone BMP-2 levels which were reverted by linagliptin and its combination with metformin." (PMID 35928902, 2022). "As expected, the thoracic aorta of DVC mice had significantly higher ALP activity, calcification and levels of RUNX2 and BMP2 compared to animals in the ND group, suggesting the successful establishment of a diabetic vascular calcification model." (PMID 35842695, 2022). "Our data showed preservation of HRECs barrier under hyperglycemic insult by BMP2 signaling inhibitors suggesting inhibition of BMP2 signaling as potential therapeutic intervention to protect blood-retinal barrier in diabetes." (PMID 33584642, 2020). "In conclusion, the current study underscores the circulating BMP2 in addition to the retinal BMP2 as a potential player and probably a biomarker in diabetes complications such as DR." (PMID 33584642, 2020). "We previously demonstrated an upregulation of retinal bone morphogenetic protein-2 (BMP2) in experimental diabetes and in retinas of diabetic human subjects." (PMID 33584642, 2020). "Our previous study showed a marked increase in retinal expression of BMP2 in experimental diabetes as well as in diabetic human." (PMID 33584642, 2020). "BMP-2 gene delivery is one option for achieving bone regeneration in patients with impaired bone healing, such as patients with diabetes or those with an irradiated site." (PMID 31387267, 2019). "Peaklevels of TGF-β1 and BMP-2 expression were delayed by 1 week in the diabetes groupcompared with the control group." (PMID 26628397, 2016). "In this study, we examinedwhether TGF-β1 and BMP-2 expressions were delayed during bone healing in type 1diabetes mellitus." (PMID 26628397, 2016). "Furthermore, ex vivo studies have shown higher expression of nuclear factor kappa B and bone morphogenetic protein 2, which are involved in the progression of aortic stenosis, in aortic valves from individuals with diabetes." (PMID 39915078, 2025). "In animal models of diabetes, BMP-2 and BMP-4 promote vascular calcification." (PMID 36909186, 2023).